LETMD1 (LETM1 domain containing 1)
Description:
Plays an essential role for mitochondrial structure and function, as well as thermogenesis of brown adipocytes. In brown adipose tissue also localizes in the nucleus where it interacts with the chromatin remodeler SMARCA4 to regulate thermogenic genes expression, such as UCP1 (By similarity). May regulate phagocytosis and inflammatory responses to lipopolysaccharide in macrophages.
Synonyms: HCCR1; HCCR; HCCR-2; HCCR-1; HCCR2; SLC55A3; 1110019O13Rik; HCRR-2
Tractability: Antibody: UniProt predicts a signal peptide or a membrane-spanning region. PROTAC: ubiquitination databases record sites on it; its protein half-life has been measured.
Gene: Protein-coding gene on chromosome 12 (51,047,962 to 51,060,426, forward strand). Ensembl gene ENSG00000050426.
Subcellular location: Mitochondrion outer membrane; Nucleus; Mitochondrion inner membrane
Subcellular location (Human Protein Atlas): Mitochondria; Nucleoli; Nucleoplasm
Gene Ontology:
Molecular function: protein binding; molecular adaptor activity; ribosome binding
Biological process: regulation of inflammatory response; regulation of phagocytosis; mitochondrion organization; positive regulation of cold-induced thermogenesis
Cellular component: mitochondrial outer membrane; mitochondrion; mitochondrial inner membrane; nucleus
Genetic constraint (gnomAD): Loss-of-function variants: 25 observed, 35.92 expected, observed/expected ratio (o/e) 0.7, 90% interval 0.51 to 0.97. The upper end of that interval is the gene's LOEUF score, 0.97, which puts it in group 4 of 6, group 1 being the genes least tolerant of losing a copy. Missense variants: 360 observed, 402.97 expected, observed/expected ratio (o/e) 0.89, 90% interval 0.82 to 0.98. Synonymous variants: 150 observed, 147.76 expected, observed/expected ratio (o/e) 1.02, 90% interval 0.89 to 1.16.
Homologues: Orthologues: chimpanzee LETMD1 (99% identical), macaque LETMD1 (88% identical), rabbit LETMD1 (87% identical), dog LETMD1 (87% identical), pig LETMD1 (86% identical), mouse Letmd1 (80% identical), rat Letmd1 (74% identical), guinea pig LETMD1 (56% identical), tropical clawed frog letmd1 (49% identical), zebrafish letmd1 (41% identical), Drosophila melanogaster CG5989 (26% identical), Caenorhabditis elegans F30F8.9 (13% identical). Paralogues in human: LETM1 (22% identical), LETM2 (21% identical).
Diseases named in the same sentence as LETMD1 in open-access papers:
LETMD1 is named in the same sentence as 15 diseases in open-access papers, as found by Europe PMC text mining. Sharing a sentence is not in itself a finding about the gene and the disease. The quoted sentences say what the papers report.
cervical cancer (6 papers, 2010 to 2025). A primary or metastatic malignant neoplasm involving the cervix. "Moreover, calcitriol suppresses the proliferation of HeLa cervical cells in part by a mechanism involving the down-regulation of the human cervical cancer oncogene (HCCR-1, LETM1 domain containing 1), which encodes a mitochondrial outer membrane protein highly expressed in cervical cancer tissue." (PMID 37240017, 2023). "LETMD1 (Human Cervical Cancer Oncogene) was detected fused to NTN4 in Sarcoma (SARC)." (PMID 32251318, 2020).
Obesity (3 papers, 2021 to 2025). Accumulation of substantial excess body fat. "We have seen that the loss of Letmd1 appears to have a deleterious effect on both cold adaptation and diet-induced obesity." (PMID 34910916, 2021). "What is unquestionable so far is that Letmd1 has a wide-ranging effect on systemic metabolism and that the loss of Letmd1 function results in prominent metabolic dysfunction encompassing obesity, glucose intolerance, and insulin resistance." (PMID 34910916, 2021). "The increased energy expenditure is accompanied by an improvement of glucose intolerance, highlighting the potential of LETMD1 as a new therapeutic target for obesity and metabolic diseases." (PMID 39897567, 2025). "SP-8356, a previously known anti-inflammation small compound, shows promising potential as a new drug lead to combat obesity and metabolic diseases via targeting LETMD1." (PMID 39897567, 2025). "In addition, we found that transplanted human beige adipocytes overexpressing LETMD1 ameliorate obesity and decrease symptoms of metabolic diseases in recipient animals, suggesting a potentially effective cellular therapy." (PMID 39897567, 2025). "Animals that lack Letmd1 have abnormal BAT morphology and dramatically reduced ability to produce heat, as well as a predisposition to diet-induced obesity and impaired glucose disposal." (PMID 34910916, 2021). "The Letmd1 KO mice are viable and grow normally, and yet its BAT phenotype is more severe, resulting in defective BAT formation, impaired acute and chronic cold adaptation, and increased susceptibility to diet-induced obesity." (PMID 34910916, 2021). "We also assessed a role for Letmd1 in the context of diet-induced obesity." (PMID 34910916, 2021). "In summary, the current study demonstrates LETMD1 as a pivotal player in enhancing non-canonical, UCP1-independent energy expenditure in human beige adipocytes, and therefore establishes it as a druggable target for obesity and metabolic diseases." (PMID 39897567, 2025).
Glucose intolerance (2 papers, 2021 to 2025). Glucose intolerance (GI) can be defined as dysglycemia that comprises both prediabetes and diabetes. "Likewise, compared with the vehicle group, mice fed with doxycycline to induce LETMD1 in UCP1 KO beige adipocytes had significantly increased VO2, energy expenditure and improved glucose intolerance." (PMID 39897567, 2025).
lung carcinoma (1 paper, 2023). "Indeed, RT–PCR results indicated that the deletion of MEN1 in lung cancer cells increased the instances of short splicing isoforms in the FAM189B, NUBP2, ENDOV and TARBP2 genes, but inhibited generation of the CPSF7, MRRF and LETMD1 splicing isoforms." (PMID 37395406, 2023).
Sepsis (1 paper, 2023). Sepsis is defined as life-threatening organ dysfunction caused by a dysregulated host response to infection. "The results of qPCR showed that the expression of NDUFB3 was higher in sepsis, whereas the expression of LETMD1 and BCKDHB were lower in SP than in HC." (PMID 37228596, 2023).
steatosis (1 paper, 2021). Increased lipid within the cytoplasm of cells. "The liver from HFD-fed Letmd1 KO mice, on the other hand, weighed more than their WT counterparts and contained some regions of steatosis without apparent changes in the inflammatory and lipid metabolism genes." (PMID 34910916, 2021).
cancer (7 papers, 2010 to 2023). A tumor composed of atypical neoplastic, often pleomorphic cells that invade other tissues. "The Letmd1 gene was initially identified as an oncogene (HCCR1 or 2) associated with human cervical cancer and has been found to be highly expressed in various cancer cells, where it is linked to tumor suppressor function." (PMID 37353518, 2023). "Genes with Lasso regression coefficients |β| > 10 include LETMD1, a known oncogene, the known tumor suppressor CDKN1B, as well as several other genes whose variants have been linked with other cancers, such as RSPO3." (PMID 27124395, 2016). "For example, matrine, which is currently used in the clinic to treat LC and HCC, inhibits cell proliferation, promotes cell differentiation and apoptosis, reduces cancer cell invasion and metastasis, and inhibits HCCR/LETMD1 mRNA and protein expression in cultured HCC cells." (PMID 26470691, 2015).
LETMD1 also shares sentences with these, for which no sentence is quoted: hepatocellular carcinoma (2 papers); metabolic disease (2); tumor (2); gastric cancer (1); Insulin resistance (1); liver cancer (1); pancreatic cancers (1); pancreatic tumor (1).